EGFR (epidermal growth factor receptor)
Diseases named in the same sentence as EGFR in open-access papers (continued):
Sharing a sentence is not in itself a finding about the gene and the disease.
tumor (continued). "Aumolertinib showed great tumor-regressing efficacy in an EGFR mutant brain metastasis model." (PMID 35677717, 2022). "EGFR is also involved in tumor development and immunotherapy-related resistance." (PMID 35582541, 2022). "For example, anti-VEGF and EGFR agents could induce tumor vascular normalization, and immunotherapy drugs including anti-PD-1 (programmed death-1) and anti-PD-L1 could remodel the immuno-microenvironment by regulating the immune cells to treat tumors." (PMID 35812432, 2022). "Interestingly, in patients with anti-EGFR therapy, those receiving primary tumor resection and anti-EGFR re-exposure showed the highest OS among all groups." (PMID 35406413, 2022). "Tumor imaging showed that EGFR inhibition alone, which could block SP cell generation, did not affect tumor growth in vivo." (PMID 35145058, 2022). "Since the phase III trials were assessed in a molecularly unselected population, one possible factor contributing to this inconsistency is the lack of predictive biomarkers to identify patients who tend to develop EGFR-dependent tumor growth and drug resistance." (PMID 35289315, 2022). "Second, there was a lack of complete data collections regarding functional status (e.g., Karnofsky and ECOG performance status scoring) and gene mutation (e.g., EGFR, KRAS and ALK) that may influence tumor progression." (PMID 35388133, 2022). "Elaidic acid, a trans fatty acids, can promote metastasis of tumor cell lines by activating EGFR." (PMID 36147842, 2022). "Interestingly, just like EGFRvIII inducing different transcriptomes and properties of tumor cells compared with the amplification of EGFRwt, EGFR S645C also potentially induces alteration of downstream genes to change the characteristics of GBM cells." (PMID 35814475, 2022). "For example, EGFR monoclonal antibody suppressed tumor metastasis by activating T cells." (PMID 35641479, 2022). "GPNMB is a newly discovered tumour-promoting factor that may promote tumour cell progression by activating the PI3K/AKT pathway by EGFR." (PMID 36090016, 2022). "We hypothesize that the variation in EGFR abundance and target affinity among patients’ tumors relates to results in high variability in tumor-tracer uptake." (PMID 35890095, 2022). "EGFR activation plays a role in HCC response to sorafenib, proposing that EGFR inhibition may enhance tumor response." (PMID 36080304, 2022). "Firstly, the mechanistic basis that allows amivantamab to selectively target tumor cells in EGFR exon 20 insertion NSCLC remains unclear." (PMID 34913823, 2022). "Preferential breakdown of blood–brain barrier in HGG improved tumor specificity of intratumoral antibody distribution relative to that of EGFR (96% vs. 80%) despite its reduced concentration (3.9 ng/mg of tissue) compared with HNSCC (8.1 ng/mg) and LAC (6.3 ng/mg)." (PMID 35332092, 2022). "Traditionally, tumor tissue samples have been utilized for EGFR testing." (PMID 36192767, 2022). "For a tumor sample without EGFR-activating mutation (#15-T), a neglectable population (0.03%) of EGFR(+)HX103(+) cells were observed." (PMID 36376325, 2022). "This theory may explain why a ten-fold reduction in EGFR affinity of nimotuzumab compared to cetuximab leads to selective binding in tumor tissue while sparing healthy tissues, thereby reducing adverse effects." (PMID 35281913, 2022). "In our study, we explore the effect of CXCL10 on persistent tumors, demonstrate that tumor and immune cells undergo crosstalk during EGFR-TKI treatment, and suggest that this crosstalk could impact the efficacy of EGFR-TKI treatment." (PMID 36612121, 2022).
tumor (continued). "The presence of EGFR T790M mutations in baseline tumor tissues did not correlate with the emergence of acquired EGFR T790M mutations detected at progression." (PMID 36232650, 2022). "Tumours harbouring mutations in genes such as EGFR and ERBB2, or gene rearrangements involving ALK, RET, or ROS1 are typically dependent on the oncogene for survival, with profound anti-tumour effects observed in response to the appropriate targeted therapy." (PMID 35326531, 2022). "As reviewed here, EGFR TKIs acutely affect numerous metabolic processes, predominantly glucose metabolism, fatty acid biogenesis, and redox homeostasis, increasing cell death and tumor reduction." (PMID 35203491, 2022). "Furthermore, the model captured the right tumor-to-lung contrast for all EGFR-TKIs and therefore was able to predict image quality." (PMID 35890095, 2022). "Importantly, the conjugation of RBCEVs with EGFR nanobody increased the percentage of CFSE‐positive tumour cells to ∼68%." (PMID 35430766, 2022). "This explains the importance of EGFR in tumor inflammations." (PMID 36438839, 2022). "Combining the previous observations with our results, we propose that ARF6 and EGFR might regulate the activity of each other to promote tumor progression by forming a positive feedback loop." (PMID 36224181, 2022). "EGFR mutations cause abnormal activation of the downstream JAK/STAT3 signalling pathway, leading to the expression of increased phosphorylated STAT3, and hence abnormal tumor proliferation, angiogenesis, invasion, and metastasis." (PMID 36185620, 2022). "Besides its high rate in NSCLC, the level of EGFR activation is also related to bad prognosis and tumor regression rate." (PMID 35164092, 2022). "In this study, we investigated whether resistance clones significantly increase shortly after exposure to EGFR-TKIs and determine the final phenotype of the resistance to EGFR-TKIs using in vitro, in vivo, and ex vivo EGFR-mutant tumor models." (PMID 35326664, 2022). "The newly found genes might render tumor cells more sensitive to EGFR-TKIs and immunotherapy for LUAD patients." (PMID 35154456, 2022). "Although both EGFR-TKIs and PD-1/PD-L1 inhibitors can regulate tumor lipid metabolism, our results suggest that the mechanisms of lipid metabolism regulation may differ, leading to significant differences in lipid metabolism between the two treatments." (PMID 36034789, 2022). "EGFRvIII increases TSSC4 expression although TSSC4 inhibits proliferation and tumor growth of cancer cells with increased activation of EGFR signaling, generating a paradox that cancer cells upregulate a protein to suppress their proliferation and tumor growth." (PMID 35309946, 2022). "The tumor tissues of our established PDX models indeed showed the several OSCC markers (EGFR: positive, CA19: partially positive, CK(AE1/AE3): partially positive, CK13: negative), indicating that those tissues were surely originated from undifferentiated OSCC tissue." (PMID 36376983, 2022). "Anti-EGFR therapy has been shown to inhibit tumor cell growth and angiogenesis in mouse models." (PMID 34575959, 2021). "Circulating tumor DNA (ctDNA) analysis has clinical utility in EGFR mutant NSCLC." (PMID 34073111, 2021). "Tests for plasma detection of EGFR mutations in the absence of a tumor sample are approved both by EMA and FDA, specifying the need to test the tissue if the result is negative due to the test’s suboptimal sensitivity." (PMID 34070940, 2021). "Nevertheless, it seems plausible that EGF could have a biological role in the tumor growth, and therefore subsequent studies should include patients treated with EGFR antagonists as well." (PMID 34115785, 2021). "However, for reasons that remain largely unelucidated, EGFR overexpressing tumours instead remain resistant to such treatments." (PMID 35052732, 2021). "In addition, the anti‐EGFR mAb in ADC can regulate tumor cell proliferation and inhibit DNA repair via modulating cell membrane or nucleus membrane EGFR." (PMID 33531889, 2021).
tumor (continued). "In our previous experiments, we found that cetuximab, an anti-EGFR monoclonal antibody, combined with celecoxib, a highly selective nonsteroidal anti-inflammatory agent, may help relieve cancer pain through reduced tumor-derived mediators in vitro." (PMID 34520454, 2021). "A possible explanation for this discordance could be due to the fact that the present study included a significantly larger proportion of patient tumours that were naïve to cetuximab treatment when the EGFR expression was determined." (PMID 33562755, 2021). "Bronchoscopic biopsy failed to obtain adequate tumor tissue to establish the diagnosis, and EGFR mutation detection using forceps biopsy and plasma samples showed EGFR wild-type." (PMID 33828971, 2021). "These three “double-positive” patients became all FISH positive at tumor re-biopsy; the two EGFR/ROS1 patients had been treated with EGFR-TKIs, and the confirmed FISH positivity at tumor re-biopsy seems to suggest an expansion of the ROS1-positive clone under EGFR target therapy pressure." (PMID 34884672, 2021). "Newly studied molecular targets, such as BLZ-100 and EGFR conjugates, are also given in the operating room, but may last in tumor tissue for up to several days." (PMID 34220688, 2021). "The diagnosis is based on clinical suspicion during EGFR-TKI treatment, detection of lung parenchymal infiltration on radiological assessment, and diagnostic exclusion of tumor progression, cardiac diseases, or other pulmonary complications, such as infectious pneumonitis." (PMID 33466795, 2021). "In our study, Tumor-Mass is lower in the EGFR-mutant group, −4.07 ± 6.05 × 106, than in the EGFR-wildtype group, 0.18 ± 3.19 × 106, indicating that tumors in the EGFR-mutant group may consist of a more partial-solid component." (PMID 33681463, 2021). "The bispecific VHH triggered CD16- and EGFR-dependent activation of NK cells and subsequent lysis of tumor cells, regardless of the KRAS mutational status of the tumor." (PMID 34771609, 2021). "However, most tumours initially responding to EGFR‐TKIs eventually recur as they acquire resistance." (PMID 34076957, 2021). "Attenuation of EGFR expression was found in high-grade tumor cells in various types of HNSCC36,37." (PMID 34272446, 2021). "In addition, abnormal expression of EGFR is closely related to neovascularization, tumor invasion and metastasis, tumor chemotherapy resistance and tumor prognosis." (PMID 33658393, 2021). "Both natural (ursolic, glycyrrhetinic, and oleanolic acids, lupeol, and dimethyl melaleucate) and semisynthetic PTs were found to inhibit tumor cell growth by decreasing phosphorylation of EGFR leading to suppression of downstream signaling (MAPK, PI3K/Akt/NF-κB and/or STAT) pathways." (PMID 34681605, 2021). "Afatinib showed favorable ORR and PFS regardless of the tumor EGFR mutation status results, similar to the findings of previous trials assessing afatinib as first‐line treatment of EGFR‐mutated NSCLC based on tumor genotyping." (PMID 33270375, 2021). "By binding to EGFR specifically, panitumumab inhibits the binding of EGFR to its ligand, thus preventing ligand-induced autophosphorylation of the receptor and activation of receptor-related kinases, thereby inhibiting tumor growth and inducing apoptosis of cancer cells." (PMID 33391438, 2021). "Among non-small cell lung cancer (NSCLC) patients with therapeutically targetable tumor mutations in epidermal growth factor receptor (EGFR), not all patients respond to targeted therapy." (PMID 33976268, 2021). "Here, we also used IHC staining to observe whether EGFR/PKC-δ/NF-κB signaling was suppressed by imipramine in CL1-5-F4/NF-κB-luc2 bearing tumor." (PMID 34765548, 2021).
tumor (continued). "Besides, the humoral immune response was found in the mutually exclusive events (CSMD3 subtype two and EGFR subtype two), which was useful for autoimmunogenic human tumor antigens and cancers." (PMID 34076361, 2021). "The 498 tumor samples were grouped according to EGFR and PI3K pathway activation." (PMID 34178665, 2021). "High level of EGFR was detected in tumor tissue from NSCLC patient." (PMID 34788230, 2021). "For multicellular 3D models including stromal cells, it may be possible to use these models to co-target EGFR alongside other factors such as stromal cell factors that promote tumor growth." (PMID 33435170, 2021). "TLR4 activation induced activation of NF-κB and MAPK signaling pathways, resulting in the release of proinflammatory cytokines (TNF-α, iNOS, COX2, PGE2, NO) favoring EGFR permanent activation as well as the release of anti-apoptosis proteins (Bcl-2, Bcl-xl) allowing tumor cell survival." (PMID 33718169, 2021). "Similarly, the EGFRvIII-targeting CAR T trial illustrated the continued presence of EGFR amplification and oncogenic EGFR ECD missense mutations despite EGFRvIII antigen loss in posttreatment tumor specimens." (PMID 34568006, 2021). "In TNBC, EGFR was overexpressed and was closely related with carcinogenesis and tumor progression." (PMID 34778045, 2021). "In conclusion, immune checkpoint inhibitors could be a recommendation for NSCLC patients having EGFR wild-type, KRAS mutation, and PD-L1 tumor proportion scores >1%." (PMID 33725808, 2021). "Efficacy outcomes were also similar in patients with EGFR Del19- and L858R-positive tumours." (PMID 33648453, 2021). "Among them, EGFR mutations are known to be associated with poor immunogenicity, T cell tumor infiltration, and a lack of response to ICIs." (PMID 34208113, 2021). "Although a high sensitivity of 88% had been observed in cases containing malignant or atypical cells, no EGFR mutation was found in cases without tumor cells in the pellet." (PMID 33828971, 2021). "EGFR is also involved in tumour infiltration, metastasis and angiogenesis." (PMID 33800113, 2021). "We therefore defined a “sensitive” tumor as one that did not harbor resistance co-mutations and in which the EGFR mutation had a high allelic frequency." (PMID 33869038, 2021). "Although the tumor microenvironment (TME) of EGFR-mutant NSCLC is immunosuppressive, EGFR-TKI may activate the TME by increasing dendritic cells and CD8+ cells, reducing Tregs, and inhibiting M2-like macrophages polarization at an early stage." (PMID 34888234, 2021). "Tumor samples harboring EGFR or ALK alterations were respectively 127 (17.7 %) and 34 (13.9 %)." (PMID 34016641, 2021). "Taking into account that the activating EGFR mutations are considered an early clonal somatic event in NSCLC development we assumed their presence at a clonal level within the tumour and related the T790M VAF to the activating EGFR mutation VAF in order to calculate T790M subclonality." (PMID 33741979, 2021). "The complexity of the mechanisms associated with acquired EGFR-TKI resistance in NSCLC has been widely demonstrated, and can be grouped into kinase domain mutations and overexpression of target oncogenes within tumor cells." (PMID 34381712, 2021). "Importantly, STAMBP knockdown suppressed LUAD tumor growth and metastasis by regulating the EGFR-mediated ERK activation in a xenograft mouse model." (PMID 34102455, 2021). "Thus, the resistance of tumours overexpressing mutant forms of the EGFR to ICI treatments was unexpected." (PMID 35052732, 2021). "What makes mAbs highly attractive is the ability of IgG1 mAbs to induce antibody-dependent cell-mediated cytotoxicity (ADCC) through Fc receptor-bearing immune cells, increasing tumor immunogenicity and providing a rationale to combine anti-EGFR mAbs with immunotherapies." (PMID 34557197, 2021). "STAMBP regulates tumor metastasis by increasing EGFR stability to trigger MAPK signaling." (PMID 34102455, 2021).
tumor (continued). "EGFR plays an important role in the progression of many types of cancer by activation of mitogenic pathways, altering cell cycle progression, and by downregulating tumor suppressor genes." (PMID 34295309, 2021). "The combination of the EGFR–MET bispecific antibody amivantamab with the third-generation EGFR TKI lazertinib also showed a synergistic inhibition of tumor growth and a good safety profile in a cohort of EGFR-mutant NSCLC patients with resistance to osimertinib in a phase 1 trial, CHRYSALIS." (PMID 34575554, 2021). "Overall, our results suggest that in heterogeneous EGFR-mutant NSCLC, tumor cells transmit EV miRNAs that may affect sensitivity to EGFR-TKIs and provide potential prognostic biomarkers for EGFR-mutant NSCLC." (PMID 33671000, 2021). "Therefore, pan-ERBB inhibitors exerted superior tumor-growth-inhibitory effects in these patients compared with EGFR-specific inhibitors." (PMID 33928034, 2021). "Empirical results have gone on to confirm the high binding specificity and selectivity of the anti-EGFR nanobody, with a demonstrated difference in uptake between tumor cells overexpressing EGFR (A431 cells) and those with a slightly more moderate expression (DU145 cells)." (PMID 33925941, 2021). "We have illustrated that ILT4 in EGFR-activated tumor cells impeded T cell immunity indirectly through the accumulation of M2-like TAMs and directly by inhibiting T cell survival and cytotoxicity, which might be the main causes of ICI resistance." (PMID 33537094, 2021). "While the addition of anti-EGFR agents to chemotherapy clearly improves tumour response, it is hypothesised that development of resistance may be faster in right-sided tumours, resulting in shorter PFS and post-progression survival." (PMID 33154570, 2021). "Notably, combination of AXL inhibitor SGI-7079 with EGFR TKI erlotinib increased the sensitivity of mesenchymal-like tumor cells to erlotinib in a mouse xenograft NSCLC model." (PMID 33170304, 2021). "Furthermore, pharmacological inhibition of EGFR signalling led to reduced FoxP3 RNA expression in EGFR expressing tumours of treated mice." (PMID 35052732, 2021). "EGFR-related NPs could target tumor cells that overexpress EGFR and also triggered NK cells-mediated anti-cancer immune responses." (PMID 34576180, 2021). "Taken together, these data suggested that inhibition of EGFR pathway activation may be responsible for the tumour‐suppressive effect of MYH10." (PMID 34738311, 2021). "Indeed, tumor response to monotherapy with EGFR-targeted antibodies is relatively low (∼10%), with a significant yet modest improvement in overall survival restricted to patients with KRAS wild-type tumors." (PMID 32646879, 2021). "Treatment-naïve patient selection for EGFR mutation assessment on cfDNA should take into account the same criteria as for tumor tissue: advanced stage or metastatic nonsquamous NSCLC, squamous NSCLC in younger patients and/or never smokers." (PMID 34680416, 2021). "It has also been discovered that PAR2 could not only itself mediate tumor progression but also transactive EGFR to cooperatively modulate cancer cell functions." (PMID 33967759, 2021). "The additional impact of the hypoxic tumor microenvironment on the expression of molecular targets of oncologic therapies, e.g., the EGFR and its downstream signaling cascades or PD-L1 illustrates the urgent need to investigate such complex interactions to improve the therapeutic response in HNSCC." (PMID 33718186, 2021).